SH2B3 (SH2B adaptor protein 3)
Diseases named in the same sentence as SH2B3 in open-access papers (continued):
Sharing a sentence is not in itself a finding about the gene and the disease.
Autoimmunity (10 papers, 2011 to 2025). The occurrence of an immune reaction against the organism's own cells or tissues. "Using in vitro assays and mouse models engineered with CRISPR/Cas9 to harbor patient Sh2b3 variants, we present data showing that rare SH2B3 variants act as hypomorphic alleles that impair B cell tolerance mechanisms predisposing to autoimmunity." (PMID 38417019, 2024). "Herein, we described two further unrelated kindreds with germline biallelic loss‐of‐function SH2B3 variants that show striking phenotypic similarity to each other as well as to the previous kindred of myeloproliferation and multi‐organ autoimmunity." (PMID 37206266, 2023). "Herein, we provide clinical and functional data on two further unrelated kindred that harbor biallelic deleterious germline SH2B3 variants and establish a novel germline syndrome with the clinical phenotype of myeloproliferation and multi‐organ autoimmunity." (PMID 37206266, 2023). "Here, we add weight to the link between SH2B3 and SLE pathogenesis by showing that SLE patient–specific novel and ultrarare variants in SH2B3 encode proteins with impaired function leading to dysregulated B cell development and tolerance that predisposes carriers to autoimmunity." (PMID 38417019, 2024). "Having demonstrated that SH2B3 variants identified in SLE patients are hypomorphic alleles resulting in immune dysregulation, we next asked whether they confer susceptibility to autoimmunity." (PMID 38417019, 2024). "Given that SH2B3 functions as inductor of a pro-inflammatory state in blood vessels, it would be interesting to determine whether R262W substitution in SH2B3 contributes to the pathogenesis of autoimmunity and thrombotic phenotype in APS." (PMID 23844121, 2013). "However, tolerated SH2B3 missense variant, rs3184504 (allele T), associated with increased TSH, was associated with increased risk of both hypothyroidism and hyperthyroidism, and in our PheWAS with increased risk of other autoimmune disorders and pleiotropic associations with many traits." (PMID 37872160, 2023). "Previous studies have connected the genetic variation in the SH2B3/ATXN2 region with CD4+ T cells counts, and a variety of autoimmune conditions, including alopecia areata and sarcoidosis." (PMID 35386719, 2022). "Furthermore, hypomorphic SH2B3 was shown to impair the negative selection of immature/transitional self-reactive B cells and accelerate autoimmunity in sensitized mice, at least in part due to increased IL-4R signaling and BAFF-R expression." (PMID 38417019, 2024). "In autoimmune Addison’s disease (AAD), candidate-gene and GWAS data converge on HLA-DR3/DR4 with replicated non-HLA signals (CTLA4, PTPN22, BACH2, SH2B3) and common AIRE effects, extending an “AIRE dosage” concept from rare monogenic APS-1 into common, complex autoimmunity." (PMID 41465179, 2025).
Stroke (10 papers, 2017 to 2025). Sudden impairment of blood flow to a part of the brain due to occlusion or rupture of an artery to the brain. "Among these, ZFHX3 and SH2B3 have already been established as linked to stroke." (PMID 39997650, 2025). "We found clear evidence for stroke risk for four loci (SH2B3, FGF5, PITX2, and KCNK3)." (PMID 37479695, 2023). "The SH2B3 gene, which encodes the lymphocyte adaptor protein LNK, has been associated with an increased risk of stroke, particularly due to its role in regulating inflammation and immune responses." (PMID 39997650, 2025). "The SH2B3 CAD/MI GWAS risk SNP resides in a GWAS hot spot, showing strong associations with numerous diseases and phenotypes including red blood cell traits, platelet volume, and eosinophil counts, as well as CAD, blood pressure, and stroke." (PMID 28122634, 2017). "SNPs in LD (R2=0.91) with rs7137828 include rs3184504 (48% frequency, p=4×10−8), a missense variant in the SH2B3 gene, associated with blood pressure, maternal birth weight, TNF-α levels, colorectal cancer, Inflammatory Bowel Disease, LDL cholesterol levels and stroke." (PMID 29227965, 2017).
hypothyroidism (9 papers, 2012 to 2024). Abnormally low levels of thyroid hormone. "Among this list, only the CTLA4, PTPN22, and SH2B3 loci show significant association with hypothyroidism after correction for 107 multiple tests." (PMID 22493691, 2012). "The SH2B3 and HLA associations reinforce the connection between hypothyroidism and autoimmune genetics." (PMID 22493691, 2012).
breast carcinoma (8 papers, 2018 to 2025). "In line with former reports, a large in silico analysis of genomic data contained in the UK Biobank showed that the SH2B3 missense variant was associated with breast cancer." (PMID 37834225, 2023). "Another study by Hung and colleagues reported that the same SH2B3 SNP on chr12q24 was associated with lung, colorectal and breast cancer." (PMID 29698419, 2018). "They found that the SH2B3 missense variant (rs3184504) was associated with breast cancer." (PMID 37834225, 2023). "Moreover, the missense mutation (rs3184504) in SH2B3 is associated with breast cancer." (PMID 39039334, 2024). "Previous studies implied a promotive role of SH2B3 in the development of breast cancer and ovarian cancer, suggesting a context-dependent function of SH2B3." (PMID 35589677, 2022). "Finally, the presence of an SH2B3 missense variant, with a potentially diminished capacity to interact with the cell membrane, might also contribute to regulating LNK activity in breast cancer." (PMID 37834225, 2023). "The highly correlated variation in the SH2B3/ATXN2/ BRAP locus (including rs3184504) is related to the age of parental death, suggesting that ATXN2 may also play a regulatory role in breast cancer." (PMID 39039334, 2024).
lung carcinoma (8 papers, 2022 to 2025). "In other words, the decrease in cell migration and invasion observed with SMYD5 knockdown was linked to the increased expression of SH2B3 in lung cancer." (PMID 38723947, 2024). "To provide molecular insights into lung cancer development, we investigated the function and underlying mechanism of SH2B3 in the regulation of lung cancer." (PMID 35589677, 2022). "To investigate the molecular mechanisms underlying the function of the TGF-β1/SH2B3 axis in lung cancer, we next determined whether and how TGF-β1 modulated JAK2/STAT3 and SHP2/Grb2/PI3K/AKT signaling." (PMID 35589677, 2022). "In the TCGA data portal, the expression of SH2B3 was decreased in lung cancer compared to normal samples." (PMID 38723947, 2024). "The overexpression of SMYD5 in lung cancer cells was found to contribute to cell migration and invasion by directly regulating the expression of the SH2B3 gene through controlled trimethylation of H4K20." (PMID 38723947, 2024). "Consistently, immunoprecipitation with SH2B3 antibody pulled down endogenous SHP2 in lung cancer cells." (PMID 35589677, 2022). "The remarkably decreased or upregulated SH2B3 mRNA and protein levels were found after transfection of lung cancer cells with sh-SH2B3 or OE-SH2B3, respectively." (PMID 35589677, 2022). "In the end, we evaluated the role of SH2B3 in lung cancer in vivo via using the nude mouse xenograft model." (PMID 35589677, 2022). "To further confirm the role of SH2B3 in lung cancer, we repeated the experiments with Calu-1 cells and observed similar effects." (PMID 35589677, 2022). "Consistently, here we observe that TGF-β1 activates JAK2/STAT3 signaling in lung cancer cells, and overexpression of SH2B3 inhibits this activation." (PMID 35589677, 2022). "In this study, we prove that SH2B3 acts as a tumor suppressor in lung cancer, and to our knowledge, this is the first study to examine the expression and function of SH2B3 in anoikis resistance and EMT of lung cancer." (PMID 35589677, 2022). "We also have demonstrated that overexpression of SH2B3 greatly suppressed lung cancer growth and liver metastasis in vivo." (PMID 35589677, 2022). "We next investigated how SH2B3 regulated anoikis resistance and malignant phenotypes of lung cancer." (PMID 35589677, 2022). "We also observed that both mRNA and protein levels of SH2B3 were significantly lower in lung cancer cells." (PMID 35589677, 2022). "Finally, we selected the upregulated SH2B3 gene and assessed its role in lung cancer metastasis because, in lung cancer cell lines, overexpression of SH2B3 decreased the number of migrated cells and the wound healing rate and induced E-cadherin expression." (PMID 38723947, 2024). "Thus, we suggest that SMYD5 is involved in lung cancer metastasis via the critical regulation of SH2B3 expression." (PMID 38723947, 2024). "Overexpression of SH2B3 suppressed lung cancer growth and metastasis in vivo." (PMID 35589677, 2022). "Src homology 2-b3 (SH2B3) is reduced in lung cancer tissues and cells." (PMID 36230714, 2022). "Low SH2B3 level was correlated with poor prognosis of lung cancer patients." (PMID 35589677, 2022). "Next, we determined the roles of SH2B3/JAK2 interaction in lung cancer." (PMID 35589677, 2022). "SH2B3 mRNA and protein levels were significantly diminished in 40 diagnosed lung cancer tissues." (PMID 35589677, 2022). "We indicated SH2B3 was diminished while TGF-β1 was elevated in lung cancer tissues and cells." (PMID 35589677, 2022). "In this study, we hypothesized that TGF-β1/SH2B3 axis participated in lung cancer development by modulating JAK2/STAT3 and SHP2/Grb2 signaling pathways." (PMID 35589677, 2022). "Besides JAK2/STAT3 signaling, we also demonstrate that SH2B3 interacts with SHP2 to inhibit the SHP2/Grb2/PI3K/AKT signaling pathway in lung cancer cells." (PMID 35589677, 2022).
lung carcinoma (continued). "Also, the in vivo animal results about the TGF-β1/SH2B3 axis in the regulation of lung cancer development and metastasis will strengthen our manuscript." (PMID 35589677, 2022). "Therefore, we conclude that SH2B3 inhibits lung cancer metastasis in vivo." (PMID 35589677, 2022). "In summary, our study is the first to illustrate the crucial roles of SH2B3 in lung cancer and reveals that TGF-β1/SH2B3 axis regulates the anoikis resistance and EMT process of lung cancer cells via JAK2/STAT3 and SHP2/Grb2/PI3K/AKT signaling pathways." (PMID 35589677, 2022). "Altogether, these results prove that SH2B3 inhibits anoikis resistance, EMT, cell proliferation, migration, and invasion of lung cancer via suppressing SHP2/Grb2/PI3K/AKT signaling." (PMID 35589677, 2022). "Taken together, our results demonstrate that SH2B3 modulates anoikis, EMT, and proliferation, migration, and invasion of lung cancer cells by suppressing JAK2/STAT3 signaling." (PMID 35589677, 2022). "In conclusion, SH2B3 restrained the development of anoikis resistance and EMT of lung cancer cells via suppressing JAK2/STAT3 and SHP2/Grb2/PI3K/AKT signaling cascades, leading to decreased cancer cell proliferation, migration, and invasion." (PMID 35589677, 2022). "Our study reports for the first time that SH2B3 regulates EMT and anoikis resistance by inhibiting JAK2/STAT3 signaling in lung cancer." (PMID 35589677, 2022). "SH2B3 inhibits JAK2/STAT3 and PI3K/AKT signaling pathways to induce anoikis in lung cancer." (PMID 36230714, 2022). "Furthermore, with a specific SH2B3 antibody, we detected JAK2 expression following SH2B3 immunoprecipitation in lung cancer cells." (PMID 35589677, 2022). "Moreover, we show that SH2B3 binds to JAK2 to inhibit JAK2/STAT3 signaling, supporting that hyperactivity of JAK2/STAT3 signaling in lung cancer cells results from diminished SH2B3 expression level." (PMID 35589677, 2022). "SH2B3 interacts with Janus kinase 2 (JAK2) and Src homology region 2-containing protein tyrosine phosphatase 2 to inhibit JAK2/STAT3 and PI3K/AKT signaling pathway-mediated anoikis in lung cancer." (PMID 36230714, 2022).
multiple sclerosis (8 papers, 2012 to 2025). A progressive autoimmune disorder affecting the central nervous system resulting in demyelination. "Previously, a SNP (rs3184504) in the SH2B3 gene was found associated with multiple sclerosis." (PMID 22916186, 2012).
endometrial cancer (7 papers, 2015 to 2025). Primary or metastatic malignant neoplasm involving the endometrium (mucous membrane that lines the endometrial cavity). "In solid tumors, genome-wide association studies have identified common susceptibility polymorphisms in colorectal and endometrial cancer near SH2B3." (PMID 31335885, 2019). "However, the only overlap from the set of ccrSNPs with other traits was the colorectal and endometrial cancer susceptibility SNP rs3184504 in SH2B3." (PMID 30093612, 2018).
erythrocytosis (7 papers, 2020 to 2025). "Germline monoallelic SH2B3 variants were also found in some patients with familial MPN, myelodysplasia (MDS)/MPN-overlap syndrome with ring sideroblasts, chronic myelomonocytic leukemia, erythrocytosis and immune cytopenia." (PMID 40481232, 2025). "In rare instances, SH2B3/LNK exon 2 mutations or polymorphisms have been reported in patients with unexplained erythrocytosis, with subnormal serum EPO levels, and absence of JAK2, MPL, and EPOR mutations." (PMID 34021251, 2021). "Occasionally, mutations in gene encoding SH2B adapter protein 3 (LNK; SH2B3) may account for or at least contribute to the erythrocytosis phenotype, and it has already been suggested that SH2B3 mutations should be a part of the investigation of idiopathic erythrocytosis." (PMID 34440324, 2021).
myeloid neoplasm (7 papers, 2019 to 2023). Proliferation of myeloid cells originating from a primitive stem cell. "Together with high‐frequency mutations, we identified rare mutations, including those in SMC3, RAD21, and SH2B3, which were also found in other myeloid neoplasms." (PMID 36916780, 2023). "Next generation sequencing (NGS) for myeloid neoplasms revealed a variant of unknown significance (SH2B3: Chr12(GRCh37): g.111886029C > T; NM_005475.2(SH2B3): c.1651C > T; p.Arg551Trp (49%))." (PMID 36051048, 2022). "Although rare, mutations and deletions of SH2B3 have previously been described in B-ALL, T-ALL and a range of myeloid neoplasms." (PMID 30816328, 2019).
asthma (6 papers, 2011 to 2024). "Among our genes that were driven by rare variants, i.e., ALOX15, CSF2RB, IL17RA, IL33, JAK2, S1PR4, and SH2B3, previous studies supported a rare variant association between IL33, which is a known asthma locus, and eosinophil count." (PMID 35935937, 2022).
colorectal cancer (5 papers, 2017 to 2025). A primary or metastatic malignant neoplasm that affects the colon or rectum. "The only significant association unrelated to BRCA2 was between colorectal cancer and SH2B3 in EUR-like individuals (p = 1.2 × 10−4, OR = 5.3)." (PMID 39799398, 2025). "Previous studies have indicated that SH2B3 suppresses colorectal carcinoma invasion, but facilitates anaplastic thyroid carcinoma growth." (PMID 35589677, 2022). "For instance, SH2B3 is downregulated and overexpression of SH2B3 reduces cancer cell invasion in colorectal carcinoma." (PMID 35589677, 2022). "The variant is also highly correlated (R2=0.91) with an exonic variant in SH2B3, previously linked to CAD, blood pressure, TNF-α, cell counts and colorectal cancer." (PMID 29227965, 2017).
lupus (5 papers, 2013 to 2025). "This work identifies a previously unappreciated role for SH2B3 in human B cell tolerance and lupus risk." (PMID 38417019, 2024). "Moreover, it was shown that SH2B3 variants in patients with systemic lupus erythematosus are predominantly hypomorphic alleles failing to suppress interferon type II signaling via JAK2-STAT1 and impairing the negative selection of self-reactive B cells in mice." (PMID 40481232, 2025). "This phenotype has not previously been reported in Sh2b3−/− mice, but the loss of MZ B cells has; although a decrease in MZ B cells has been observed in lupus-prone B6.Yaa mice, this was cell-extrinsic as a result of enhanced activation by antigen-bearing DCs." (PMID 38417019, 2024). "Here, we show that unlike the variant found exclusively in healthy controls, SH2B3 rare variants found in lupus patients are predominantly hypomorphic alleles, failing to suppress IFNGR signaling via JAK2-STAT1." (PMID 38417019, 2024).
psoriasis (5 papers, 2012 to 2025). An autoimmune condition characterized by red, well-delineated plaques with silvery scales that are usually on the extensor surfaces and scalp. "Common genetic variants such as FUT2, UBE2L3, CDKAL1, SH2B3 and apolipoprotein E are more frequently found in psoriasis patients, having multiple functions that would explain their dual role in susceptibility to psoriasis and MS." (PMID 40003621, 2025).
atherosclerosis (4 papers, 2018 to 2025). A disease characterized by the build-up of fatty material and calcium deposition in the arterial wall resulting in partial or complete occlusion of the arterial lumen. "Moreover, SNPs in SH2B3 (Lnk) are associated with MPN, multiple sclerosis and atherosclerosis, though atherosclerosis is not an autoimmune disease but a chronic inflammatory state." (PMID 29614027, 2018).
glioblastoma (4 papers, 2015 to 2023). The most malignant astrocytic tumor (WHO grade IV). "It has been documented that SH2B3 contributes to glioblastoma progression by transducing IL-6/gp130/STAT3 signaling." (PMID 37426414, 2023).
ovarian carcinoma (4 papers, 2020 to 2023). A malignant neoplasm originating from the surface ovarian epithelium. "In contrast to hematologic malignancies, SH2B3 was reported to activate the JAK/STAT3 and ERK1/2 pathways to promote the progression of triple-negative breast cancer and act as a positive signal transduction regulator in ovarian cancers." (PMID 33937225, 2021).
autoimmune hepatitis (3 papers, 2021 to 2024). Hepatitis caused by autoantibodies. "Multiple studies indicated that SH2B3 was related to the occurrence of autoimmune Hepatitis." (PMID 38373892, 2024).
autoimmune thyroid disease (3 papers, 2021 to 2023). Inflammatory disease of the thyroid gland due to autoimmune responses leading to lymphocytic infiltration of the gland. "To date, a single kindred has been described with germline biallelic loss‐of‐function SH2B3 variants characterized by early onset developmental delay, hepatosplenomegaly and autoimmune thyroiditis/hepatitis." (PMID 37206266, 2023). "SH2B3 belongs to the SH2B adaptor family of proteins and has been associated with the involved development of CeD gastrointestinal and extraintestinal manifestations, CeD-associated conditions (autoimmune thyroid disease and T1D), and small bowel mucosal damage." (PMID 37108375, 2023).
cardiac hypertrophy (3 papers, 2020 to 2025). "In contrast to this, intracardiac SH2B3/LNK expression was found to be associated with pressure overload cardiac hypertrophy regulation." (PMID 32629392, 2020). "Significant overexpression of the SH2B3 gene promotes the activation of the Akt signaling pathway, which can promote cardiac hypertrophy and fibrosis and lead to the deterioration of cardiac function." (PMID 41027922, 2025). "In detail, SH2B3 aggravates cell fibrogenesis in cardiac hypertrophy." (PMID 35692373, 2022).
ischemic stroke (3 papers, 2019 to 2022). A stroke disorder caused by obstruction of blood flow to the brain, due to thrombotic (local blood clot formation) or embolic (due to a blood clot or other material traveling from another site) event. "For example, a recent clinical study with 18,000 ischemic stroke patients and 70,000 controls identified SNPs in SH2B3 and ALDH2 linked to ischemic stroke, which were also associated with blood pressure." (PMID 31514409, 2019).
myelodysplastic syndrome (3 papers, 2021 to 2025). A clonal hematopoietic disorder characterized by dysplasia and ineffective hematopoiesis in one or more of the hematopoietic cell lines. "Germline mutations in SH2B3 have been reported in different diseases, particularly myelodysplastic syndrome and JMML." (PMID 36123612, 2022).